EPO (erythropoietin)
Diseases named in the same sentence as EPO in open-access papers (continued):
Sharing a sentence is not in itself a finding about the gene and the disease.
anemia (continued). "In response to anemia, CDA type II patients have elevated EPO levels and show erythroid hyperplasia in the bone marrow, with reticulocyte counts within the normal range, yet remaining relatively low." (PMID 33672223, 2021). "Anemia was more common and treated more often in KTR, partly because most anemic KTRwere already using erythropoietin at the study onset, whereas most NT-PDP wereincident patients." (PMID 33346316, 2021). "Recombinant human erythropoietin (rHuEPO, epoetin alfa) was approved by the Food and Drug Administration (FDA) in 1993 for the treatment of anemia in cancer patients." (PMID 33535496, 2021). "Hypoxia-induced activation of HIF as well as pharmacologic inhibition of HIF-hydroxylases induces transcription of genes including erythropoietin (EPO) and its receptor transferrin in vivo and in vitro, thereby ameliorating anemia." (PMID 34571989, 2021). "HIF-A has three known isoforms (HIF-1A, HIF2A, HIF-3A), amongst which HIF2A is mainly involved in regulation of EPO synthesis; HIF2A knockout mice demonstrate a hypocellular marrow and anemia as a result of inadequate EPO production." (PMID 34021251, 2021). "However, high levels of EPO are administered in cases of anemia (around 300–500 IU/kg), doses of between 60 and 350 IU/kg are administered for doping purposes, and the highest doses of EPO are used to promote neuroprotection in stroke cases, for example, with levels between 10 k and 40 k IU/kg." (PMID 34594222, 2021). "FGF23 knockout mice became polycythemic through decreased apoptosis of erythroid progenitor cells and increased erythropoietin (EPO), whereas administration of FGF23 decreased endogenous EPO and exacerbated anaemia." (PMID 33832448, 2021). "These costs far outweighed the lower cost of the use of tranexamic acid, erythropoietin (EPO), oral treatments of anemia, intravenous iron therapy, and cell salvage utilization." (PMID 33693019, 2021). "Subsequently, we identified anti-EPO and anti-EPOR antibodies in the blood of patients with autoimmune diseases, such as CKD accompanied by anemia and systemic lupus erythematosus." (PMID 34059008, 2021). "Anemia is a well-known consequence of chronic kidney disease (CKD); it is mainly due to a relative insufficiency of erythropoietin synthesis by the failing kidneys." (PMID 33670704, 2021). "An increase in circulating EPO but normal ferritin levels and near compete depletion of BMAT, suggest that FGF15INT-KO VSG mice have bone marrow dysfunction leading to anemia of chronic disease." (PMID 34362888, 2021). "Although EPO levels are elevated in patients with CIA, this elevation remains insufficient for the degree of anemia." (PMID 33842333, 2021). "It has been described that anaemia persists in 50% ESRD patients under long-term haemodialysis, despite appropriate recombinant human erythropoietin (rhEPO) administration and iron supplementation." (PMID 32994444, 2020). "Erythropoietin (EPO), the master hormone regulating red blood cell (RBC) formation is commonly used in the clinics to treat anemia in patients with chronic kidney disease, heart failure, and cancer." (PMID 33117187, 2020). "The primary use of the erythropoiesis stimulating agents (ESAs) EPO and HIF‐PHDi is to treat the anemia of CKD." (PMID 32476270, 2020). "Anemia is a complication of chronic kidney disease (CKD), primarily due to insufficient secretion of erythropoietin (EPO) by the kidney." (PMID 32850902, 2020). "Except for treating anemia after TBI, EPO has a potential neuroprotective effect acting as biological antioxidant." (PMID 33178833, 2020). "Previous cellular and animal experiments have revealed that JPYS stimulated the transcriptional expression of EPO in HEK293T cells and improved the anemia symptoms by increasing the serum EPO level and HIF-α protein in 5/6 nephrectomized rats." (PMID 33178327, 2020).
anemia (continued). "Ever since clinical trials in 1987 proved the efficacy of recombinant human EPO (rhEPO) for the treatment of anemia in CKD, EPO therapy has been established." (PMID 32635646, 2020). "Erythropoietin (EPO), a naturally occurring cytokine used to treat anemia by inhibiting apoptosis in erythrocyte progenitors, has been shown to be neuroprotective." (PMID 33014446, 2020). "Administration of exogenous erythropoietin for CKD patients, especially those receiving dialysis, is the standard treatment for anemia." (PMID 33331829, 2020). "Recombinant human EPO has become a central replacement therapy for a large number of patients with CKD, but despite improving anemia, patients with a higher targeted hemoglobin had more adverse events." (PMID 32476270, 2020). "An “anemia control model” (ACM) was recently constructed and used to support the dosing of darbepoetin, an erythropoietin-stimulating agent (ESA), in patients with anemia and end-stage kidney disease who require hemodialysis." (PMID 32625083, 2020). "In our study, we found a higher level of anemia-related indexes and less exposure to ABT in the rHu-EPO group compared with patients in control group." (PMID 33213494, 2020). "In anemia, a major complication of chronic kidney disease, HIF stabilizers are currently used to restore circulating EPO levels." (PMID 33084574, 2020). "Anaemia in ESRD patients has been attributed to inflammation, partly because a uremic milieu promotes an inflammatory response, which would inhibit EPO synthesis." (PMID 32994444, 2020). "Since anemia is a frequent comorbidity found in ESRD and dialysis patients, key elements were targeted by AI software: erythropoietin-stimulating agents, hemoglobin target, and iron treatment dosing." (PMID 32596403, 2020). "Furthermore, anemia treated with ESAs continuously failed to obtain a sustained response, which may also be caused by EPO antibodies." (PMID 32318578, 2020). "With declining renal mass, patients with CKD lose the ability to produce erythropoietin (EPO) and develop anemia due to low blood iron, inflammation, hemorrhage, EPO resistance, or relative EPO deficiency." (PMID 32476270, 2020). "Although a relative EPO deficiency may contribute to anemia in ESRD, it is not the sole cause." (PMID 32968161, 2020). "Erythropoietin (EPO) is a glycoprotein hormone which promotes red cell replenishment and is also a global biotherapeutic medicine widely used to treat anaemia resulting, for example, from chemotherapy." (PMID 30972470, 2019). "Combined treatment of Siwu granules with EPO increased the expression of EPO and EPOR in the renal tissues and inhibited oxidative stress and inflammatory factors, improving the renal function and anemia." (PMID 31915448, 2019). "In agreement with this, our current study revealed that the protein level of HIF-2α and EPO was robustly upregulated by JPYS treatment, which supported JPYS would have benefits in anemia of CKD via HIF activation." (PMID 30941190, 2019). "Erythropoietin (EPO) stimulates erythroid progenitor cell and early erythroblast maturation and is mainly used in anemia treatment." (PMID 31787868, 2019). "Besides reduced EPO production, other factors may contribute to anemia in CKD, including reduced erythrocyte life-span, hyperparathyroidism, inhibition of erythropoiesis by uremic toxins, iron metabolism disorders and impaired dietary iron and vitamin absorption." (PMID 30794672, 2019). "Because a vital erythroid growth factor, erythropoietin (EPO), is secreted from renal interstitial fibroblasts [renal EPO-producing (REP) cells], anemia arises as a major complication of CKD." (PMID 31798631, 2019). "While effective therapies are available for anemia of CKD, including supplemental iron, recombinant human EPO (rhEPO) and its analogs, and blood transfusions, each has significant limitations." (PMID 31619187, 2019).
anemia (continued). "Erythropoietin alfa (EPO) is a short acting erythropoiesis-stimulating agent (ESA) and has been a primary choice for treating anemia in patients with CKD for the past twenty years." (PMID 30866856, 2019). "Prior to the development of EPO therapy in the late 1980s, androgens were the only option for treating CKD-related anemia in men." (PMID 31798530, 2019). "Anemia is a consequence of chronic kidney disease (CKD), principally because of the depreciation of and reduced synthesis of erythropoietin." (PMID 31614529, 2019). "In this study, the improvement of anemia in CKD rats by JPYS treatment and the involvement of HIF signaling in JPYS-treated rats, including renal functions, hematological parameters, and EPO concentrations, as well as HIF activation, were investigated." (PMID 30941190, 2019). "The origins of anemia of chronic kidney disease (CKD) are multifactorial, including impairment of both renal EPO synthesis as well as intestinal iron absorption." (PMID 29738538, 2018). "Although anemia in CKD is a multifactorial disorder, it is well explained by insufficient EPO, a hormone that stimulates red blood cell production in the bone marrow in response to low oxygen levels in the blood." (PMID 29740119, 2018). "Since the discovery of erythropoietin, ESAs have been used to treat anemia in various patient groups, including patients with cancer or CKD, where anemia is a common problem." (PMID 30687083, 2018). "The concentrations of hemoglobin and EPO in the serum of CKD patients are significantly lower, and CKD patients are more prone to anemia and anemic hypoxia." (PMID 30429775, 2018). "Serum creatinine and BUN as well as hematocrit, hemoglobin (Hb) and plasma erythropoietin (EPO) levels were monitored to assess renal function and anemia, respectively." (PMID 29415057, 2018). "Anemia is a common feature in patients with chronic kidney disease (CKD), and it is mainly attributable to the relative decrease in erythropoietin (EPO) production by the kidneys, absolute or functional iron deficiency, and shortened red cell survival." (PMID 29933406, 2018). "Anaemia is a very common problem in patients with end-stage kidney disease (ESKD) and the use of erythropoietin-stimulating agents (ESA) has revolutionised its treatment." (PMID 29178879, 2017). "However, the erythropoietin (EPO)-mediated feedback during anaemia brings in reticulocytes which could be a cue for an imminent improvement in the environment, although this seems unlikely because the presence of reticulocytes generally also correlates with the appearance of adaptive immunity." (PMID 28768894, 2017). "Erythropoietin (EPO) is a well-known hormone with classic hematopoietic functions and clinically used for the treatment of anemia." (PMID 28383559, 2017). "Two patients receiving SOF/RBV developed progressive anaemia that required reduction of the RBV dosage and erythropoietin administration." (PMID 28388935, 2017). "Especially in low-income and middle-income countries, most anemia arises from an inadequate nutritional supply (iron or vitamins), and anemia resulting from chronic disease might be corrected through treatment (for example, erythropoietin therapy for chronic kidney disease)." (PMID 29212527, 2017). "Erythropoietin (EPO), a kidney-derived peptide hormone necessary to produce red blood cells in bone marrow, is prescribed for anemia patients who suffers from renal anemia and anemia of prematurity." (PMID 28288167, 2017). "HIF-2 is the key regulator of hypoxic EPO induction and is required for normal erythropoiesis, and HIF-2 deletion from renal tissue results in severe anemia." (PMID 28468297, 2017). "Anemia is a common complication of ESRD, primarily the consequence of reduced EPO production and of uremia- and resultant hyperparathoyroidism-related resistance to this hormone." (PMID 27717322, 2016). "Anemia is common among patients with CKD, due in part to reduced erythropoietin production as kidney function declines." (PMID 26823182, 2016).
anemia (continued). "Erythropoietin (EPO) is a secreted cytokine that is FDA approved and used in the clinic for the treatment of anemia." (PMID 27299810, 2016). "The TB group showed anemia as Hb and HCT levels that were significantly lower than the NTB group, with elevated RBC counts and EPO levels." (PMID 27068103, 2016). "Erythropoietin (EPO), a 165 kDa secreted glycoprotein, was first characterized as a hematopoietic factor and has been widely used for the clinical treatment of anemia." (PMID 27274711, 2016). "In spite of the increased serum EPO levels found in CRF rats, anemia persisted in these animals throughout the protocol, as well as the reticulocyte production, suggesting a blockade and/or a reduction in the activity of EPO." (PMID 25867633, 2015). "Since exercise and EPO partially improve cachexia in the C26 hosts, such combined approach has been tested also in the LLC-bearing mice, where anemia is markedly severe." (PMID 26636649, 2015). "Previous studies in HIV patients have reported autoantibodies to several human proteins, including erythropoietin (EPO), interferon-α (IFN-α), interleukin-2 (IL-2), and HLA-DR, as potential mediators of anemia or immunosuppression." (PMID 26599070, 2015). "Moreover, there has been a recent resurgence of interest in the mechanisms of hepatic EPO production stimulated by the suggestion that hepatic EPO synthesis could replace the need for recombinant EPO administration in patients with anemia secondary to chronic kidney disease." (PMID 25422368, 2015). "Among 89,000 patients with anemia and CKD (96.7% male, median age 77.5), 7.1% initiated erythropoietin stimulating agents within a year of diagnosis of anemia, while 30.8% initiated iron therapy and 16.5% used blood transfusions in the same time span." (PMID 24392162, 2014). "Therapy was well tolerated; side effects included dyspnoea, pruritus and anaemia, leading to the application of 250mg BID ursodeoxycholic acid and 30μg erythropoietin/week." (PMID 25047566, 2014). "Recent studies provide evidence that BFU-E and CFU-E can undergo limited self-renewal, particularly in response to acute stress such as anemia and that the self-renewal of CFU-E is dependent on the action of EPO." (PMID 24478716, 2014). "Furthermore, data on pre-or postmenopause or medications such as metformin, iron supplements, or erythropoietin which could potentially change the anaemia or cardiovascular risk profile status were not included in the analysis." (PMID 23509453, 2013). "Recombinant human erythropoietin (rHuEpo) for the treatment of CKD and patients with anemia related to cancer has been available since 1989." (PMID 23555091, 2013). "Restoration of endogenous secretion of erythropoietin (EPO) and its impact on the outcome of anemia have been assessed in several studies." (PMID 24346775, 2013). "Erythropoietin (EPO), a hematopoietic growth factor, is predominantly produced in the kidney, and has been widely used in patients with anemia from renal diseases and myelodysplasia following chemotherapy or radiotherapy." (PMID 23326455, 2013). "Therefore, a study evaluating the levels of anti-EPO antibodies in malaria anaemia will be of interest to assess the benefits and/or predict (un)expected complications that may arise in the administration of exogenous EPO as therapeutic measure in malaria anaemia cases." (PMID 23978045, 2013). "Secondary RLS in ESRD patients might be correlated with iron deficiency which has concurrence with anemia (due to lack of erythropoietin) also in the absence of anemia in these patients and so iron treatment is an option to manage ESRD patients presenting RLS with anemia." (PMID 24307876, 2013). "These pro-inflammatory cytokines lower the production of erythropoietin, the renal hormone responsible for RBC formation, thereby leading to anaemia." (PMID 23282136, 2013).
anemia (continued). "Despite the frequent expression of EPO and EPOR in RCC, approximately 35% of RCC patients develop anaemia, whilst only 1-5% experience paraneoplastic polycythaemia." (PMID 23305401, 2013). "Even though PHZ treatment results in an increase of serum EPO levels, this hormone is still rate-limiting for RBC expansion, as application of exogenous EPO results in increased RBC counts after PHZ induced anemia." (PMID 23975731, 2013). "In conclusion, EPO expression is increased in patients with CHF and in those with CHF complicated by anemia, and the increase correlates with the severity of CHF." (PMID 24223667, 2013). "Erythropoietin (EPO) is a hematopoietic growth factor that readily crosses the BBB and is routinely used clinically to treat anemia." (PMID 24019878, 2013). "Although the patient received human granulocyte colony stimulating factors (hG-CSF) and erythropoietin (EPO) repeatedly, anemia and leukopenia relapsed soon." (PMID 22497910, 2012). "In the present retrospective study, the impact of EPO treatment on the symptomatic anaemia of GIST patients treated with imatinib and the predictive factors of EPO efficacy was investigated." (PMID 22950685, 2012). "In this study, we investigated the efficacy of EPO treatment on the anaemia of GIST patients treated with imatinib and the predictive factors of EPO efficacy." (PMID 22950685, 2012). "Anaemia commonly occurs in patients with chronic kidney disease (CKD), as a result of insufficient production of erythropoietin (EPO) by the kidneys." (PMID 22768256, 2012). "Anemia is a common complication of end-stage renal disease (ESRD) and results from decreased erythropoietin (EPO) production, reduced bone marrow response to EPO, shortened red blood cell survival, and chronic iron loss." (PMID 22203913, 2011). "The prolonged anemia observed in mice treated with rhuEPO plus LPS and CpG ODN suggests that the inoculations led to a break in tolerance to the endogenous (mouse) EPO, which is needed to maintain the hematocrit stable." (PMID 21203556, 2010). "As up to 50% of our patients start off with anemia to consider PBD, they will require recombinant human erythropoietin, and this makes it clinically and financially unattractive." (PMID 20877596, 2010). "The pathogenesis of anemia in CKD is multifactorial and predominately driven by impaired erythropoietin production; however inflammation negatively impacts erythropoiesis and is associated with resistance to erythropoietic therapy." (PMID 20368776, 2010). "Previous reports demonstrated that the decrease of hepcidin expression by experimentally induced anemia in animals is dependent on erythropoiesis, since it could be abolished or blunted by inhibitors of erythropoiesis such as irradiation, carboplatin, doxorubicin or EPO-blocking antibodies." (PMID 19924283, 2009). "Friedman reported 5 cases in which patients with severe anemia and PDR had substantial reduction of macular hard exudates after treatment with systemic EPO." (PMID 19930719, 2009). "In order to identify factors potentially affecting anaemia management, we assessed the effect of age, gender, etiologies of end stage renal disease (ESRD) and co-morbidities on Hb level and EPO dose." (PMID 19077225, 2008). "ESAM 2003 already showed increased mean EPO doses compared to ESAM 1998 in all participating countries, certainly explaining most of the improvement of anaemia control." (PMID 19077225, 2008). "Anemia, a common manifestation of chronic kidney disease (CKD), results primarily from inadequate renal secretion of erythropoietin." (PMID 17910755, 2007). "EPO stimulates the production of RBC and has shown promise for the treatment of HS-related anemia." (PMID 41007072, 2025). "Seven years ago, she was found to have normocytic normochromic anemia with no increase in reticulocytes and only a mildly elevated erythropoietin level of 54.8 mIU/mL and was started on darbepoetin alfa with the diagnosis of renal anemia." (PMID 40161151, 2025).